NOS2 (nitric oxide synthase 2)
Diseases named in the same sentence as NOS2 in open-access papers (continued):
Sharing a sentence is not in itself a finding about the gene and the disease.
depression (17 papers, 2015 to 2024). "The A/T-G/G genotype of c.−89A > T(rs7943316) in CAT and c.−227G > C(rs10459953) in NOS2 was associated with a risk of depression (p = 0.001)." (PMID 32111088, 2020). "The risk of depression increased twofold with combined T/T-T/Tgenotypes of NOS2 c1823C > T(rs2297518) and GPx4 c." (PMID 32111088, 2020). "T/T-C/T genotypes of SNVs c.−89A > T(rs7943316) in CAT and c.1823C > T(rs2297518) in NOS2 increased the risk of depression (p = 0.002), while the T/T-T/T genotype reduced the risk (p = 0.036)." (PMID 32111088, 2020). "In vitro experiments showed that BTS may achieve depression-inducing effects by downregulating Nos-2 and Cox-2 to inhibit NO production, stimulating pro-inflammatory cytokine production and inducing neuroinflammatory responses in microglia." (PMID 36440427, 2022). "However, the gene–gene analyses revealed that a risk of depression increased five-fold with genotypes such as T/T-T/T of SOD2 c.47T > C(p.Val16Ala)(rs4880) and NOS2 c.1823C > T(p.Ser608Leu)(rs2297518) polymorphisms (p = 0.013)." (PMID 32111088, 2020). "We aimed to determine whether genetic deletion of Casp1, Nos2 and Ifngr affects depression- and anxiety-like behaviours in mice, either in the absence of stress or in response to CUS." (PMID 31015500, 2019). "This study shows the effects of chronic administration of agomelatine on expression and the methylation status of Sod1, Sod2, Gpx1, Gpx4, Cat, Nos1, and Nos2 in the brain stricture and blood in the chronic mild stress (CMS) animal model of depression." (PMID 32545212, 2020). "Part of the components of Si-ni San can bind to NOS2 and ESR1, which may play a role in improving depression combined with anxiety through these pathways." (PMID 39247617, 2024).
viral infection (17 papers, 2009 to 2025). "An increased expression of the Ass1 gene in piMφ suggests that arginine metabolism is active to allow bioavailability of this amino acid as a NOS2 substrate, since NO is essential to inhibit viral infection." (PMID 39296294, 2024). "In animals models of coxsackievirus B3 infection, this nitrosylation is likely to be derived from NOS2, which is predominantly found in activated macrophages, since NOS2 knock-out mice displayed higher titers of viral infection." (PMID 25405382, 2015). "One of the well known effector mechanisms induced by IFN-γ after viral infections is enhancement of NOS2 expression in phagocytes." (PMID 22666512, 2012). "Meanwhile, ARND also downregulated the levels of mRNA expression of proinflammatory transcription factors (NF-κB and c-Rel), proinflammatory cytokines (IL-1β, IL-6, TNF-α and CCL2) and NOS2 in vitro, which may be useful to attenuate the inflammatory response upon viral infection." (PMID 35897044, 2022). "Thus, IFN-induced NOS2 represents antiviral activities, and this, in turn, may exhibit another mechanism through which IFNs hinder viral infections such as influenza." (PMID 32161622, 2020). "The expression of NOS2 is known to be modulated by IFN-regulatory factor 1 (IRF1); this transcription factor is, indeed, induced by IFNγ during the host immune response to viral infections." (PMID 37893073, 2023). "After virus infection, Piezo1 channel activation was downregulated by GsMTx4 treatment, leading to reduced PAD4 expression, ROS production and NET formation in neutrophils, and TNFα and NOS2 expression was decreased in macrophages from the BALF and lung." (PMID 39890818, 2025).
colorectal cancer (16 papers, 2014 to 2025). A primary or metastatic malignant neoplasm that affects the colon or rectum. "The aim of this study was to determine the NOS2 polymorphism influence on colorectal cancer development with regard to the tumor localization." (PMID 38398251, 2024). "Regarding the biosynthesis of nitric-oxide, colorectal cancer is strongly associated with chronic inflammation and nitric-oxide produced by NOS2 is associated with the initiation and progression of the disease." (PMID 32107391, 2020). "Although NOS2’s increased expression may be associated with Gamma Knife treatment, its potential role in colorectal cancer treatment remains underexplored, warranting further investigation to elucidate the underlying mechanisms." (PMID 40568960, 2025). "The stratification of colorectal cancer patients into subgroups based on tumor location revealed differences in tumor characteristics as well as in the frequency of the minor allele A in the NOS2 genotype." (PMID 38398251, 2024). "NOS2 is expressed higher in the left- and right-colorectal cancer low-risk group." (PMID 35265525, 2022). "Our study aimed to investigate the balance between nitric oxide synthase-2 (NOS2) and arginase-1 (ARG1) expression and its association with immune contexture and clinical outcome in cetuximab-treated colorectal cancer patients." (PMID 41573553, 2025). "First, our study demonstrated that NOS2/NO expression at the mRNA, protein, and plasma levels was significantly higher in patients with colorectal cancer than in controls (p < 0.0001)." (PMID 41573553, 2025). "MDSCs belong to colorectal cancer-infiltrating immune cells, which express Arg-1, iNOS/NOS2, and ROS and can induce immune tolerance by inhibiting the proliferation and activation of CD8+ T cells." (PMID 38684668, 2024). "Elevated iNOS (product of NOS2 gene) levels have been observed in a number of human cancers, including colorectal cancer, and it has often been a predictor of poor outcomes." (PMID 38398251, 2024). "Its relation with colorectal cancer has been investigated and high levels of NOS2 expression where related to colorectal cancer progression and development and with poor prognosis." (PMID 29522543, 2018). "We used multiple immunofluorescence techniques to detect the expression of CD19, CD163, C-kit, CD68, NOS2, mast cell tryptase, and CD16 markers in colorectal cancer tissues and surrounding normal tissues on the same slide." (PMID 35646079, 2022). "In colorectal cancer, an improved prognosis also correlates with macrophage infiltration, regardless of phenotype (based on nitric oxide synthase 2 [NOS2] or CD163 expression)." (PMID 34876704, 2022). "A study investigating the impact of 5-FU chemotherapy on gut inflammation showed that in AOM/DSS-induced colorectal cancer model mouse treated with 5FU, significantly elevated expression of intestinal inflammatory genes was found, including TNF-α, MCP-1, NOS2, IL6, IL1-β, and FOXP3." (PMID 34337082, 2021). "The effect of inhibiting arginase 1 (ARG1) and nitric oxide synthase 2 was assessed using the small molecule inhibitors NOHA and L-NMMA, respectively, and was found not to rescue T cell proliferation inhibited by colorectal cancer patient’s CD14 + cells." (PMID 34727230, 2022).
endotoxemia (16 papers, 2009 to 2023). "Our findings are at variance with these data, as the Nos2-deficient mice in our study demonstrated an impaired NO-production and a decreased number of perfused vessels during prolonged endotoxemia, similar to control mice." (PMID 34769369, 2021). "In endotoxemia, AVP impairment in late phase of endotoxemia is associated with an increase in the synthesis of pro-inflammatory mediators during and the consequent late production of NO by NOS2." (PMID 33430014, 2021). "Both AE-ITU and l-NMMA resulted in NOS2 inhibition and attenuated the liver dysfunction and circulatory failure in the liver as caused by endotoxemia." (PMID 25699985, 2015). "This enhanced NO production was associated with an impaired intestinal microcirculation, as judged from the improved perfusion after inhibition of NOS2 activity or in Nos2-deficient mice exposed to endotoxemia." (PMID 24465919, 2014). "Furthermore, downregulation of Nos3 expression during endotoxemia may further contribute to the impaired NO production during endotoxemia in these Nos2-deficient animals." (PMID 34769369, 2021). "L-citrulline supplementation during endotoxemia enhanced jejunal NO production in control and Nos2−/− mice (n = 5, both p < 0.05) and was ~ 3-fold higher in control than in Nos2−/− mice." (PMID 34769369, 2021). "L-citrulline supplementation during endotoxemia resulted in enhanced plasma citrulline concentrations in control, Nos2−/− and Nos3−/− mice." (PMID 34769369, 2021). "We therefore investigated the effect of L-citrulline supplementation in Nos2−/−, Nos3−/−, and Nos2−/−/Nos3−/− mice on intracellular arginine availability, jejunal NO production and microcirculatory flow in a prolonged endotoxemia model." (PMID 34769369, 2021). "Competition for the amino acid arginine by endothelial nitric-oxide synthase (NOS3) and (pro-)inflammatory NO-synthase (NOS2) during endotoxemia appears essential in the derangement of the microcirculatory flow." (PMID 34769369, 2021). "Reduced arginase-1 activity in Arg1fl/fl/Tie2-Cretg/− mice resulted in increased inflammatory response and NO production by NOS2, accompanied by a depressed microcirculatory flow during endotoxemia." (PMID 24465919, 2014). "Our findings reveal that the enhanced NO production in endothelial cells and jejunal tissue of Arg1fl/fl/Tie2-Cretg/− mice during endotoxemia was largely NOS2-derived." (PMID 24465919, 2014). "One of the key players for inducing vasoplegia after endotoxemia is nitric oxide (NO), produced by the inducible NO-synthase (iNOS, NOS2)." (PMID 22970242, 2012). "Our previous work employed MGBs in vitro and in vivo to confirm an important role for TF-binding to AT-rich DNA regions in transactivation of the NOS2 promoter and in attenuating mortality and hypotension during murine endotoxemia." (PMID 20498830, 2010). "Plasma levels of LPS also increased nearly 20-fold and recruitment of eosinophils was dramatically reduced in the intestines, confirming that the acute mortality of Il4−/− mice was due to the increased Th1/NOS2/endotoxemia and reduced Th2 effector response." (PMID 19360123, 2009). "Here again, death was associated with increased Th1 cytokine production, hepatic and intestinal histopathology, increased NOS2 activity, elevated liver enzymes, and endotoxemia." (PMID 19360123, 2009). "The HFD caused intestinal permeabilization, endotoxemia, reduced tight junction protein expression, increased nicotinamide adenine dinucleotide phosphate (NADPH) oxidase and nitric oxide synthase (NOS)-2 expression, oxidative stress, and the activation of redox-sensitive signals." (PMID 37836436, 2023). "Historically, deletion or inhibition of NOS2 was hypothesized to be the key to prevent or treat the detrimental effects of endotoxemia on microvascular perfusion." (PMID 34769369, 2021).
endotoxemia (continued). "As observed by our group, in tissue-specific arginase deficient mice, lacking arginase in hematopoietic cells, NOS2 produced significantly more NO during endotoxemia in the tissues and in macrophages compared to control." (PMID 25699985, 2015). "In another porcine endotoxemia model, the supplementation of the selective NOS2 inhibitor mercaptoethylguanadine (MEG) prevented hypotension and was capable of decreasing the amount of expired NO, however this did not result in an improved hepatosplanchnic metabolism." (PMID 25699985, 2015). "Supplementation of the selective NOS2 inhibitor N-(3-(Aminomethyl)benzyl)acetamidine (1400W), did not affect systemic hemodynamic parameters during prolonged hyperdynamic porcine endotoxemia, however was capable of attenuating the impaired intestinal oxygenation and energy state." (PMID 25699985, 2015). "Indeed, Nos2−/− mice subjected to endotoxemia showed an improved jejunal microcirculation compared with Arg1fl/fl/Tie2-Cretg/− + LPS-treated mice." (PMID 24465919, 2014). "The HFD caused intestinal permeabilization, endotoxemia, and reduced expression of tight junction proteins (occludin, ZO-1, and claudin-1) in the ileum, as well as increasing NADPH oxidase (NOX1 and NOX4), NOS2, oxidative stress, and the activation of redox-sensitive signals (NF-κB and ERK1/2)." (PMID 37836436, 2023). "In addition, in the absence of NOS2 a decreased defense against bacterial inoculation was observed, which underlines that NOS2 also exhibits a protective role during endotoxemia." (PMID 25699985, 2015). "Indeed, the different time points of peak expression of NOS2 and arginase in murine endotoxemia models, after, respectively, 20 min, 4–6 h and 12 h for NOS2 and 12–36 h for arginase may indicate this inhibitory effect." (PMID 25699985, 2015). "This increased NOS2 activity is suggested to contribute to the decreased NOS3 derived NO production and the depressed microcirculatory flow during endotoxemia." (PMID 25699985, 2015). "The effects of endotoxemia and L-citrulline supplementation were similar in control and Nos2−/− mice, which shows that NOS2 does not contribute to the vasodilatory effect of NO in jejunal villi." (PMID 34769369, 2021). "Normally, endotoxemia results in an increased expression of Nos2 mRNA and protein, which leads to an increased NO-production, but this overexpression of Nos2 does not enhance hypotension." (PMID 34769369, 2021). "Endotoxemia reduced the total number of perfused vessels and the number of perfused vessels per villus in control and Nos2−/− mice, but did not alter these parameters in Nos3−/− or Nos2−/−/Nos3−/− mice." (PMID 34769369, 2021). "However, due to non-homogeneous expression of Nos2 in tissues, shunting of the microvascular flow during endotoxemia occurs." (PMID 34769369, 2021). "Furthermore, we showed that, in the absence of arginase-1 in endothelial cells or macrophages, only NOS2-derived NO production significantly increased during endotoxemia, whereas NOS3-derived NO production did not benefit from the arginase-1 deficiency." (PMID 34769369, 2021). "Furthermore, excessive NOS2-mediated NO production during endotoxemia in non-homogeneously distributed inflammatory cells results in a maldistribution of NO and a “hyperdynamic” microcirculation by shunting." (PMID 34769369, 2021). "To evaluate this methodology, we used mice with lipopolysaccharide- (LPS-) induced endotoxemia, as this model is well characterized by an inflammatory reaction with an NADPH-oxidase-dependent oxidant burst and elevation in RNS through the inducible nitric oxide synthase (NOS-2) pathway." (PMID 31249650, 2019). "However, due to the increased NOS2 induced NO production this did not result in beneficial effects upon the microcirculation during endotoxemia." (PMID 25699985, 2015). "The mortality was not due to acute Th1/NOS2-mediated hepatotoxicity or endotoxemia." (PMID 19360123, 2009).
endotoxemia (continued). "This study investigated the role of NOS2 and NOS3 combined with/without citrulline supplementation on the NO-production and microcirculation during endotoxemia." (PMID 34769369, 2021). "This study confirms that L-citrulline supplementation enhances de novo arginine synthesis and NO production in mice during endotoxemia with a functional NOS3-enzyme (control and Nos2−/− mice), as this beneficial effect was absent in Nos3−/− or Nos2−/−/Nos3−/− mice." (PMID 34769369, 2021).
glioblastoma (15 papers, 2015 to 2025). The most malignant astrocytic tumor (WHO grade IV). "The first aim of this study was to evaluate the NOS2 expression in human glioblastoma primary culture to verify its association with the capacity of generating neurospheres." (PMID 28424427, 2017). "In vitro, OV-Cmab-hCCL5-infected human glioblastoma cells supernatant increased the phagocytic activity and IL-1, IL-6, IL-12, and NOS2 expression of human monocyte-derived macrophages." (PMID 39196415, 2024). "Clinically, a positive correlation exists between Ly6G+ cells and the NOS2-NO-ID4 regulatory axis in patients diagnosed with recurrent glioblastoma." (PMID 30804471, 2019). "In particular, Ly6G+ cells promote conversion of glioblastoma cells to glioblastoma stem cells (GSCs) through the NOS2-NO-ID4 regulatory axis." (PMID 30804471, 2019). "NOS2 knockdown by RNA interference strategy or by specific inhibitors, negatively affects the proliferation and invasiveness of glioblastoma cells and was able to reduce the progression of subcutaneous and intracranial human glioma xenografts in mice." (PMID 28424427, 2017). "Anti-NOS2A (Anti Nitric Oxide Synthase 2A) is a 1.9 kb intronless polyadenylated lncRNA expressed in meningomas and glioblastomas, transcribed from the NOS2A (17q23.2) locus." (PMID 26082843, 2015). "The relevance of nitric oxide synthase 2 (NOS2) as a prognostic factor in Glioblastoma Multiforme (GBM) malignancy is emerging." (PMID 31226744, 2019). "We selected four human cancer cell lines derived from aggressive tumor types that are known to express NOS2 and synthesize NO in vivo (MDA-MB-231 and MDA-MB-668 are TNBC, PC-3 is prostate, and U251 is glioblastoma)." (PMID 39966373, 2025). "In an immunocompetent glioblastoma model treated with HSV, the administration of TGFβ decreased TAM infiltration and their TNFα and NOS2 expression." (PMID 39196415, 2024). "It was found that Id4 increases platelet-derived growth factor (PDGF) and nitric oxide synthase 2 (NOS2) expression levels in glioblastoma cells; this positive regulatory circuit of PDGF-NO-Id4 enhances the self-renewal of glioblastoma cells." (PMID 32708313, 2020). "Many studies have shown that low flux nitric oxide (NO) produced by inducible NO synthase (iNOS/NOS2) in various tumors, including glioblastomas, can promote angiogenesis, cell proliferation, and migration/invasion." (PMID 30781428, 2019). "It has been reported that hypoxia regulates the expression of pro-inflammatory genes like COX-2, NOS2, PTX3 in glioblastoma cancer stem cells." (PMID 29719610, 2018). "NOS2 has been reported highly expressed in grade III astrocytomas and glioblastomas, with a positive correlation between its expression and tumor grade." (PMID 30227679, 2018). "In intracranial U87 xenografts, immunostaining revealed that bevacizumab-resistant glioblastoma showed an increased amount of TAMs and increased M2/M1 ratio, defined by M2 markers (Arg-1, TGF-β, MMP9) and M1 markers (NOS2, CXCL10, IL-1β), compared to bevacizumab-sensitive glioblastoma." (PMID 34209679, 2021).